SSX6P (SSX family member 6, pseudogene)
Description:
Could act as a modulator of transcription.
Synonyms: psiSSX2; formerly SSXP2; SSX6
Gene: Transcribed unprocessed pseudogene on chromosome X (48,109,981 to 48,119,630, forward strand). Ensembl gene ENSG00000171483.
Diseases named in the same sentence as SSX6P in open-access papers:
SSX6P is named in the same sentence as 5 diseases in open-access papers, as found by Europe PMC text mining. Sharing a sentence is not in itself a finding about the gene and the disease.
SSX6P shares sentences with these, for which no sentence is quoted: melanoma (2 papers); synovial sarcoma (2); cancer (1); medulloblastoma (1); tumor (1).